XIAP (X-linked inhibitor of apoptosis)
Diseases named in the same sentence as XIAP in open-access papers (continued):
Sharing a sentence is not in itself a finding about the gene and the disease.
tumor (continued). "Moreover, as XIAP levels increase with radio chemotherapy it is possible that a subset of more resistant tumour cells survive this treatment and may be resistant to further adjuvant treatment." (PMID 26071313, 2015). "In addition, XIAP has been found to an important anti-autophagy factor in tumor cells." (PMID 25831237, 2015). "Interestingly, loss of XIAP function sensitizes human tumor cell lines to TRAIL, but not inducers of the intrinsic death pathway." (PMID 20067634, 2010). "NFKB is activated TRADD-, TRAF3- and FADD-dependently and also plays a key role in the survival of tumor cells by inducing expression of anti-apoptotic genes such as Bcl2, Bcl2l1, vascular endothelial growth factor (VEGF), and X-linked inhibitor of apoptosis (XIAP)." (PMID 19077262, 2008). "Thus, XIAP may represent a novel and tumour-selective therapeutic target for anticancer drug design." (PMID 15685240, 2005). "Importantly, we could demonstrate for the first time in RCCs that XIAP mRNA expression levels significantly increased from early (pT1) to advanced tumour stages (pT3) and – quite similarly – also with tumour dedifferentiation." (PMID 15328523, 2004). "Since XIAP expression is known to be also post-transcriptionally regulated, we additionally performed Western blot analysis in arbitrarily selected RCC samples of early and advanced tumour stages and could confirm the tumour stage-dependent increase of XIAP expression on the protein level." (PMID 15328523, 2004). "The tumor suppressor ARTS can act as an adaptor, recruiting the E3 ligase SIAH to XIAP, leading to auto‐ubiquitination and degradation of XIAP." (PMID 41362701, 2025). "Constitutive NF-κB activation in tumor cells increases the expression of prosurvival genes (e.g., BCL2, XIAP), angiogenic factors (VEGF, IL-8), and metastasis-promoting molecules (CXCR4, MMPs)." (PMID 40562870, 2025). "PCNA, BCL2, TRAF2, XIAP and FKBP5 expression levels in whole RNAs extracted by 36 tumor tissue samples were quantified as relative expression, using expression from healthy donor PBMCs as a reference sample (=1)." (PMID 41256864, 2025). "NFκB facilitates tumor cell survival, proliferation, and angiogenesis by regulating the expression of target genes such as cyclin D1, IL6, BCLXL, BCL2, XIAP, and VEGF." (PMID 39203892, 2024). "It was stated that overexpression of XIAP decreased the sensitivity of RCC cells to apoptosis and created favorable conditions for tumor cell survival and development." (PMID 38410284, 2024). "Immunohistochemical staining of the tumor tissue demonstrated strong expression of ERCC-1, MRP-2, and XIAP in most of the HOXB9 OE/SKOV3-injected group tumors compared with the control SKOV3-injected group tumors." (PMID 36674764, 2023). "Paraffin-embedded tumor samples were stained immunohistochemically for CD3, CD20, CD38, CD56, CD66b, CD117, and CD163 and XIAP." (PMID 36472768, 2023). "The results indicated that NAIP, BIRC2, BIRC3, XIAP, BIRC5, and BIRC6 showed significantly higher expression levels in tumor tissues than in normal tissues." (PMID 37781078, 2023). "In order to determine the association between the anti-tumor effects observed in vivo and the inhibition of MNK1 downstream signaling, XIAP and MCL1 levels were analyzed from tumor samples by western blotting." (PMID 37111758, 2023). "The levels of NAIP, BIRC2, XIAP, and BIRC6 were significantly elevated in the subgroups of tumor stages 1-3 compared to their levels in the normal subgroups, with no discernible differences in their levels in the subgroup of tumor stage 4." (PMID 37781078, 2023).
tumor (continued). "In the 20 pairs of clinical samples we collected, rt-PCR results showed that ZNF678, ARID1A, XIAP, MIS18BP1, and MBTPS2 were highly expressed in tumor tissues." (PMID 36249009, 2022). "When we examined isolated tumor tissues, immunoblotting demonstrated that MX69-treated groups had reduced expression ofMDM2, XIAP, and c-Myc and increased expression of pro-apoptotic factor NOXA." (PMID 35326742, 2022). "MiR-214-3p, for example, serves as a tumor suppressor by targeting ABCB1 and XIAP proteins, preventing multi-drug resistance and stimulating apoptosis." (PMID 35322101, 2022). "Our results indicated that tumor tissues of mice exposed to BDMC showed relatively lower levels of anti-apoptotic proteins (Bcl-2) and XIAP when compared to the control group." (PMID 35008959, 2022). "Of note, the dual cIAP/XIAP antagonist ASTX660 significantly delays growth of both HPV- and HPV+ human tumor xenografts in combination with radiotherapy." (PMID 33718169, 2021). "Drawing insights into the functions of these genes, several tumor proliferation-related genes (EGFR, NOTCH1, and MAP2K1) and the anti-apoptosis related genes (BCL2L1, XIAP) were detected." (PMID 33637972, 2021). "We found tumor tissues with high FAM83B expression had high BCL2 and CCND1 expression, and had low apoptosis inhibitor XIAP expression." (PMID 33423038, 2021). "The results of Western blots also showed the levels of apoptosis related protein (XIAP and Survivin) significantly down-regulated in VALD-3 (20 mg/kg/d) tumor tissues and the increased cellular apoptosis were confirmed by TUNEL staining." (PMID 34294779, 2021). "Anti-apoptosis- and proliferation-related proteins, such as CyclinD1, XIAP, C-FLIP, and MCL-1, were all decreased in the tumor tissues in the combination group." (PMID 33922992, 2021). "Immunohistochemical staining of Ki67 and XIAP showed lower levels of Ki67-positive tumor cells and decreased CD31-positive microvessels and XIAP expression in SLCO4A1-AS1 knockdown tumors." (PMID 34650909, 2021). "Protein concentrations for PC9, PC3, XIAP and SMAC from n = 120 patient tumours, quantified by reverse phase protein array, together with a median APAF1 expression were used to simulate apoptosis execution." (PMID 32341447, 2020). "The overexpression of oncogenic proteins, such as Cyclin-D1, MCL-1, C-FLIP, XIAP, MMP-9, MMP-2, uPA, and VEGF, are correlated with constitutive NF-κB activity and involved in promoting tumor progression in CRC." (PMID 32429376, 2020). "Compared to the NCI60 analysis, we further revealed distinct expression pattern of BIRC5 and BIRC7 and synchronized expression for NAIP, BIRC2, BIRC3, XIAP and BIRC6 in multiple tumor types." (PMID 31964418, 2020). "This is likely attributable to the lack of specific ligands for BIRC3, as well as overlooked by its low expression in most tumor cells (detectable in only 8% of 60 tumor cell lines) compared to other IAP proteins, such as cIAP1 and XIAP." (PMID 32718354, 2020). "Our results suggested that XIAP, RICTOR and HDAC2 either independently or cooperatively contribute functionally to the tumour suppressive effects of miR-500a-5p in CRC cells." (PMID 30737378, 2019). "A recent study indicated that XIAP inhibitors synergize with TRAIL to induce apoptosis and suppress various tumor growths." (PMID 31083595, 2019). "MG132 treatment blocked tumor growth inhibition induced by NQO1 knock out, accompanied with increased level of SIRT6 and XIAP." (PMID 31842909, 2019). "The expressions of KNG1, XIAP and VEGF were detected in the tumor tissues of mice injected with U87-MG cells." (PMID 30068373, 2018). "BAX and XIAP are important apoptosis-regulatory proteins, and cyclooxygenase-2 (COX2) is an inflammatory enzyme whose activity can inhibit the apoptosis of tumor cells." (PMID 30093972, 2018).
tumor (continued). "For better understanding of the apoptosis efficacy of XIAP 3′UTR in vivo, we examined the expression of Bcl-2, Bax and Caspase-3 in tumor samples immunoreactivity." (PMID 28186968, 2017). "Depletion of XIAP also enhanced the active GTP-bound form of Cdc42 with a concomitant increase in actin-rich filopodial protrusions in normal and tumor cells." (PMID 28661476, 2017). "XIAP has a tumor-promoting role in ATC and depletion of XIAP increases the chemosensitivity of ATC cells." (PMID 29221164, 2017). "In summary, we demonstrated that XIAP 3′UTR increases cell proliferation, migration, invasion, tumor growth, EMT phenotype and decreases cell apoptosis by binding to endogenous miRNAs." (PMID 28186968, 2017). "We also identified another mechanism for XIAP's attenuation of tumor cell immune responsiveness when we noted that granzyme-mediated ADCC required ROS generation and that this was suppressed in XIAP-overexpressing cells, contributing to ADCC resistance." (PMID 26821068, 2016). "NF-κB plays a critical role in the regulation of proteins involved in the cell survival (Bcl-2, XIAP), proliferation (cyclin-D1), invasion (MMP-9, RANKL), angiogenesis (VEGF), and inflammation (COX-2, TNF-α), all contribute to the tumor progression." (PMID 26487364, 2015). "To verify the protein array results, we performed Western blots and confirmed CUDC-101 treatment reduced the level of survivin, XIAP, and β-catenin, which are upregulated in ATC and contribute to the highly aggressive behavior of this tumor." (PMID 25940539, 2015). "It was found that SMAC mimetics allow sensitization of tumor cells for apoptosis induction by releasing caspases from the inhibitory interaction with IAP proteins, particular XIAP and that SMAC mimetics have complex effects on NFκB and TNF signaling." (PMID 25101252, 2014). "Therefore, we speculate that the rs999885 variant genotypes could contribute to miR-106b-5p overexpression and then suppress cell survival, metastasis and tumor recurrence through reducing the expression levels of XIAP, thereby finally led to a good prognosis of HCC patients in our study." (PMID 24416400, 2014). "Upon addition into the cytosol, the XIAP-neutralizing peptides AVPIAQK and ATPFQEG only moderately heightened the (cyt-c + dATP)-induced caspase-3-like activity in some NSCLC tumours." (PMID 24626292, 2014). "Consequently, downregulation of the anti-apoptotic gene products BCL2/BCL-XL/XIAP via NF-κB inhibition may allow tumor cells to be sensitive to apoptosis induction by low doses of TMZ, as is the case for U251 showing strongly potentiated apoptosis despite being resistant to single treatments." (PMID 23533755, 2013). "XIAP is an eye catching member of the IAP family, indulged in malignant effects of tumor cells especially cell invasion, proliferation, angiogenesis and chemoresistance." (PMID 23613836, 2013). "Furthermore IL-6 may also provide tumor cells with mechanisms to escape cell death induced by stress and cytotoxic drugs, such as increased expression of several survival proteins, i.e. Bcl-2, Bcl-xL, Mcl-1, survivin, and XIAP." (PMID 23517603, 2013). "To begin to elucidate mechanisms mediating the improved efficacy of the combinedtherapy group, we assessed the expression of several proteins involved ininvasiveness and angiogenesis (MMP-2, XIAP, OPN, and VEGF) in the tumor tissueof the treated groups." (PMID 22569271, 2012). "Genetic targeting of XIAP, as well as IAP antagonists that mimic Smac (an endogenous inhibitor of IAPs), strongly enhances tumor cell sensitivity to TRAIL." (PMID 24213315, 2012). "XIAP, Survivin and Bcl-2 met all these criteria and are characterized as upregulated in PDAC cell lines as well as native tumor tissue." (PMID 20646298, 2010).
tumor (continued). "In contrast, knockdown of XIAP in DU145 cells has been shown to increase sensitivity to cisplatin induced apoptosis and its knockdown in other tumour cells has been shown to sensitise for cytotoxic drugs such as mitomycin C, doxorubicin, etoposide and taxanes." (PMID 19549337, 2009). "Mounting evidence confirms that XIAP, the most potent anti-apoptotic protein among IAPs, is responsible for primary or acquired TRAIL resistance in tumor cells." (PMID 19895686, 2009). "Thus, XIAP may represent a novel and tumor-selective therapeutic target for anticancer drug design." (PMID 16953886, 2006). "We, therefore, calculated the ratio between antiapoptotic XIAP and proapoptotic Smac/DIABLO mRNA expression levels in different tumour stages." (PMID 15328523, 2004). "In contrast, the mRNA and protein levels of its antagonist Smac/DIABLO remained constant, resulting in an increased expression ratio between XIAP and Smac/DIABLO during tumour progression." (PMID 15328523, 2004). "The standard curve with a correlation coefficient of 0.99 was used for a relative quantification of the copy numbers obtained from XIAP, Smac/DIABLO and GAPDH in each tumour sample." (PMID 15328523, 2004). "We consistently found that BCL2L1 and XIAP were highly expressed specifically in tumor cells but not in non-tumor cells." (PMID 39122703, 2024). "Since ARTS is an apoptosis inducer by antagonizing the anti-apoptotic proteins, such as XIAP, BCL-2, and BCL-XL it might act as a tumor suppressor." (PMID 36565718, 2023). "We identified XIAP, but not cIAP‐1/2 as target for SM to augment the anti‐tumor effect of chemotherapy." (PMID 36416169, 2023). "Twelve patients with a XIAP-positive tumor, but no patient with a XIAP-negative tumor developed invasive disease at the time of relapse (p=0.0015)." (PMID 36845731, 2023). "In the H226 xenograft, tumor growth was suppressed by DCA/Nic and partially mediated by apoptosis (downregulation of Bcl-2 and XIAP), anti-proliferation (decrease in expression of PCNA and Akt), G2/M arrest (CDK7 downregulation) and suppressed migration (decline in expression β-catenin)." (PMID 36304150, 2022). "Nicotine has been established to promote XIAP protein stabilization and surviving transcriptional induction through the Akt pathway, thereby inhibiting the apoptosis effects of chemotherapeutic drugs on NSCLC tumor cells." (PMID 34796198, 2021). "Tumor masses from HCC PDX mice treated with omacetaxine and negative control were utilized to prepare frozen sections, which were then stained for the c-Myc, MET, β-catenin, XIAP, and cyclin D1." (PMID 34003798, 2021). "WT USP11 (but not the C318A mutant) deubiquitinates and stabilizes X-linked inhibitor of apoptosis (XIAP) in a xenograft mouse model, which results in the suppression of anoikis and apoptosis and enhanced tumor growth." (PMID 33919439, 2021). "Thus, XIAP acted as a link between MAPK and NFkB signaling to control IBC proliferation and tumor aggression." (PMID 32340135, 2020). "Moreover, tumour progression‐related proteins such as MMP‐2, MMP‐9, uPA, VEGF, Cyclin D1 and XIAP were all decreased by imipramine in U‐87 MG and GBM8401 cells." (PMID 32149465, 2020). "First, imipramine may inhibit ERK/NF‐κB signalling transduction and thus reduced tumour progression‐related proteins expression, including MGMT, MMP‐2, MMP‐9, uPA, VEGF, Cyclin D1 and XIAP." (PMID 32149465, 2020). "Furthermore, the decreased expression of survivin and XIAP and enhanced staining of TUNEL were observed in tumor tissues from mice treated by Sur-X, which indicated the induction of apoptosis by Sur-X in vivo." (PMID 32381104, 2020). "Degrading XIAP, as opposed to allosteric inhibition, should require smaller amounts of drugs to promote tumor killing." (PMID 32182843, 2020). "Embelin, a potent, nonpeptidic cell-permeable inhibitor of X-linked inhibitor of apoptosis protein (XIAP), exerts anti-tumor effects by limiting IL-6/STAT3 activation and the Th17 immune response in GBs." (PMID 31698775, 2019).
tumor (continued). "Furthermore, IHC analysis showed that NQO1 knock-out was related with reduced level of SIRT6, XIAP and increased level of cleaved PARP in tumor tissues." (PMID 31842909, 2019). "Sept4/ARTS‐Null mice show accelerated spontaneous tumor development, elevated XIAP (but not cIAP1) levels, and increased numbers of stem cells that are resistant to cell death." (PMID 29460395, 2018). "In vitro data suggests that XIAP inhibition by natural compound, embelin, improved the response to PARP inhibition by olaparib and serves as a guide to translate this to substantial anti-tumor activity in vivo." (PMID 30647872, 2018). "Moreover, the level of KNG1 was also enhanced in the tumor tissues of mice injected with SHG-44 cells and the expressions of XIAP and VEGF were inhibited (P < 0.05)." (PMID 30068373, 2018). "When protein expression was assessed in tumor samples by immunoblotting, there was down-regulation of XIAP and inactivation of AKT and subsequent down-stream targets thereby suggesting that tumor regression in xenografts were following the same pattern as the in vitro studies in BC cell lines." (PMID 28893228, 2017). "Nevertheless, one has to keep in mind, that the expression of XIAP without any relation to the tumour site did result in a decreased overall survival." (PMID 28486965, 2017). "In OCCCa tissues, cytoplasmic XIAP immunopositive cells displayed a heterogeneous distribution within tumor lesions and appeared to colocalize with pSmad2, but not LEFTY, immunoreactivity." (PMID 28969018, 2017). "Moreover, XIAP inhibitor Embelin and autophagy inducer EBSS dramatically abrogated miR-23a ASO-decreased tumor cell migration and invasion." (PMID 29113338, 2017). "Since survivin interacts with IAP family member XIAP in several cellular processes such as inhibition of programmed cell death and activation of transcription factor NF-κB, we also aimed to unravel the potential role of XIAP in GEP-NEN tumor biology." (PMID 28039474, 2017). "Whereas shRNA mediated XIAP knock down reduced cell viability and tumor growth of NEC cells, small molecule smac mimetics failed to inhibit cell proliferation in vitro and were therefore not further validated in our in vivo mouse models." (PMID 28039474, 2017). "This suggests that miR-671 diminishes the inhibition of miR-7 expression through ciRS-7; improves the miR7 level in tumor cells; contributes to the increase of downstream target oncogenes, such as EGFR and XIAP; and promotes vascularization, metastasis and reproduction of tumor cells." (PMID 28143578, 2017). "Nonetheless, caspase binding did not account for the totality of XIAP's ability to reduce the sensitivity of tumor cells to ADCC." (PMID 26821068, 2016). "Using RCC cell lines, we have revealed that inhibition of GSK-3 results in decreased expression of NF-kB target genes Bcl-2 and XIAP leading to a subsequent increase in RCC apoptosis and the anti-tumor effect of sorafenib, TKI available for treatment of mRCC in clinical practice." (PMID 27387559, 2016). "Moreover, FeDC-E NPs inhibited phosphorylation of the EGFR as well as the EGFR–ERK–NF-κB signaling pathways of the EGFR overexpressing cells along with the expression of the downstream tumor promoting proteins MMP-9 and XIAP." (PMID 27833124, 2016). "To validate our major in-vitro finding of Hsp60 upregulation and concomitant XIAP downregulation following CFEA treatment, we performed immunohistochemistry (IHC) to determine the level of these two proteins in harvested control and CFEA treated tumor tissues." (PMID 26672742, 2015). "When we compared matched tissue pre- and post- radio chemotherapy we found that XIAP levels increased significantly during treatment in both normal and tumour tissue, while Smac levels did not change." (PMID 26071313, 2015).